ENSG00000293171 (novel transcript)
Gene: Long non-coding RNA gene on chromosome 19 (37,779,637 to 37,792,772, forward strand). Ensembl gene ENSG00000293171.
Gene Ontology:
Biological process: SRP-dependent cotranslational protein targeting to membrane, signal sequence recognition
Cellular component: signal recognition particle, endoplasmic reticulum targeting